SPOCK1 (SPARC (osteonectin), cwcv and kazal like domains proteoglycan 1)
Diseases named in the same sentence as SPOCK1 in open-access papers (continued):
Sharing a sentence is not in itself a finding about the gene and the disease.
gingival overgrowth (1 paper, 2020). Excessive growth of the gingiva either by an increase in the size of the constituent cells (gingival hypertrophy) or by an increase in their number (gingival hyperplasia). "Our findings suggest a novel mechanism triggered by SPOCK1 interactions with TGF-β1 and MMP-9 that induces several signaling pathways in drug-induced gingival overgrowth." (PMID 32555336, 2020). "We found that SPOCK1, TGF-β1, and MMP-9 mRNA and their protein products were significantly higher in gingival overgrowth (GO) samples compared to non-overgrowth controls." (PMID 32555336, 2020). "We demonstrated that the expression of SPOCK1, TGF-β1, and MMP-9 in calcium channel blocker-induced gingival overgrowth is higher than that in non-overgrowth tissues." (PMID 32555336, 2020).
glaucoma (1 paper, 2021). Increased pressure in the eyeball due to obstruction of the outflow of aqueous humor. "SPOCK1 encodes a member of the SPARC family and is associated with glaucoma." (PMID 34440692, 2021).
gynecological cancers (1 paper, 2025). "It has been determined that SPOCK1 expression is associated with many clinicopathological features in gynecological cancers such as OV, CSEC, and UCEC." (PMID 40001977, 2025). "The roles of SPOCK1 in gynecological cancers were examined using data from the TCGA or GEPIA2 database." (PMID 40001977, 2025). "Our goal was to use cancer databases to look into the SPOCK1 protein in three different forms of gynecological cancer (OV, CESC, and UCEC) and analyze its impact as a biomarker for cancer diagnosis and prognosis." (PMID 40001977, 2025). "This study has demonstrated the relationship between SPOCK1 protein expression and gynecological cancers." (PMID 40001977, 2025). "However, there is limited information on the importance of SPOCK1 in gynecological cancers in the literature." (PMID 40001977, 2025). "Although SPOCK1, a member of the Sparc protein family, has been studied in many types of cancer such as lung, prostate, breast, and colorectal, the link between SPOCK1 and gynecological cancers is not well known due to the very few studies conducted on gynecological cancers." (PMID 40001977, 2025). "Although our results suggest that SPOCK1 is associated with the regulation of immune cell infiltration in the TME in gynecological cancers, further research is needed to determine the exact relationship between immune cell infiltration and SPOCK1 expression in gynecological cancers." (PMID 40001977, 2025). "However, we believe that our findings will provide ideas for other studies to be conducted in determining the relationship between gynecological cancers and SPOCK1 protein." (PMID 40001977, 2025). "SPOCK1 may be a potential prognostic and therapeutic target for gynecological cancers." (PMID 40001977, 2025). "However, the relationship between gynecological cancers and SPOCK1 has not been sufficiently investigated yet." (PMID 40001977, 2025).
hemoglobinopathy (1 paper, 2022). "The expression gene analysis showed that PTGFR (downregulated) and GPR56 (upregulated) are differentially expressed in placentas of women with sickle cell anemia as well as SPOCK1 (downregulated) and ADCY4 (upregulated) in placentas of women with hemoglobinopathy HbSC." (PMID 36129958, 2022).
injury (1 paper, 2025). Damage inflicted on the body as the direct or indirect result of an external force, with or without disruption of structural continuity. "ECM-related proteins such as SPOCK1 and CSPG5 were also integrated within the network, consistent with their potential involvement in matrix remodeling during acute brain injury." (PMID 41152969, 2025).
lung fibrosis (1 paper, 2022). "Among the genes in this gene set is SPOCK1, an extracellular proteoglycan that induces epithelial to mesenchymal transition through the TGF‐β1 pathway, with mesenchymal transition being an important mechanism of airway remodelling and SPOCK1 representing a potential novel target in lung fibrosis." (PMID 35673765, 2022).
melanoma (1 paper, 2020). A malignant, usually aggressive tumor composed of atypical, neoplastic melanocytes. "The cell cycle and taste transduction gene sets were enriched in high-expression groups of ARHGAP6 and ADAMTS15, respectively, whereas primary immunodeficiency and melanoma were enriched in the CHRD and SPOCK1 high-expression groups, respectively." (PMID 32218218, 2020).
myocardial infarction (1 paper, 2020). Gross necrosis of the myocardium, as a result of interruption of the blood supply to the area, as in coronary thrombosis. "Fibroblasts from GA patient 2 (sub-cluster 7), meanwhile, expressed elevated amounts of SPOCK1 (Avg-Log FC: 0.99), CRLF1 (Avg-Log FC: 1.38), and COMP (Avg-Log FC: 1.35), a cartilage protein that is upregulated in matrix-producing fibroblasts after myocardial infarction." (PMID 33053333, 2020).
neuroblastoma (1 paper, 2022). Neuroblastoma (NB) is the most common solid, extracranial childhood tumor. "Similar interaction has been identified in neuroblastoma in which significantly decreased SPOCK1 RNA levels were detected in SOX9 knockout neuroblastoma cells." (PMID 35221802, 2022).
oesophageal cancer (1 paper, 2023). "The LCN2/LOXL2/MMP9 complex remodels the ECM and activates the FAK/AKT/GSK3β signalling pathway to enhance SPOCK1 expression, promoting the migration and invasion of oesophageal cancer cells." (PMID 37753805, 2023). "Therefore, LCN2/LOXL2/MMP9 activated the FAK/AKT/GSK3β signalling pathway to enhance SPOCK1 expression and remodel the ECM, thus promoting the migration and invasion of oesophageal cancer cells." (PMID 37753805, 2023).
oral cancer (1 paper, 2020). "Another very important finding from our study is that NFD might induce EMT through TGF-β1-mediated SPOCK1 up-regulation, which could drive hypertensive patients with oral cancer toward a higher risk of metastasis, as EMT is one of the main mechanisms of cancer metastasis with poor prognosis." (PMID 32555336, 2020).
periodontitis (1 paper, 2023). An acute or chronic inflammatory process that affects the tissues that surround and support the teeth. "We first confirmed that Spock-1 overexpressing (Spock1-Tg) mice showed significantly thicker gingiva and greater alveolar bone loss than WT mice in response to ligature-induced experimental periodontitis." (PMID 38156070, 2023). "The expression of Il-2 tended to be downregulated in Spock1-Tg mice at basal and increased by experimental periodontitis in both WT and Spock-1Tg mice." (PMID 38156070, 2023). "DIGO was induced by the combination of CsA administration and experimental periodontitis was significantly enhanced in Spock1-Tg mice compared to that in WT mice." (PMID 38156070, 2023). "Among the Matrix metalloproteinases (MMPs), gingival Mmp2 expression was significantly upregulated by experimental periodontitis in both WT and Spock1-Tg mice." (PMID 38156070, 2023). "Combination of CsA and periodontitis exhibited additive suppression of E-cadherin and upregulation of Vimentin in Spock1-Tg mice." (PMID 38156070, 2023). "The combination of CsA and experimental periodontitis resulted in the lowest E-cadherin and the highest Vimentin expression in the gingiva of Spock1-Tg mice among all of the mice groups." (PMID 38156070, 2023). "We accomplished this by using a silk ligature model of periodontitis and the transgenic Spock1-Tg mice that induce the DIGO phenotype by facilitating EMT." (PMID 38156070, 2023). "Notably, experimental periodontitis-induced fibrosis was significantly enhanced in CsA-treated Spock1-Tg mice compared to that in CsA-untreated Spock1-Tg mice, which was consistent with the gingival thickening data." (PMID 38156070, 2023). "Spock1-Tg mice showed an increased fibrotic area in the gingival connective tissue in response to ligature-induced periodontitis compared to WT mice, whereas the extent of epithelial thickness in Spock1-Tg mice with periodontitis was comparable to that of WT mice with periodontitis." (PMID 38156070, 2023). "Furthermore, CsA and SPOCK1-related EMT could enhance gingival overgrowth under periodontitis in additive manner." (PMID 38156070, 2023). "The present study showed that MMP-2 levels in the gingiva were upregulated in both WT and Spock1-Tg mice, and active-MMP-2 levels in the gingiva were upregulated in Spock1-Tg mice and experimental periodontitis." (PMID 38156070, 2023). "The current model using Spock1-Tg mice with CsA administration in combination with experimental periodontitis is not fully mimic human DIGO even though it shows highly fibrotic gingival overgrowth that almost covers the tooth crown." (PMID 38156070, 2023). "Next, we detected EMT-related molecules to confirm the EMT characterization in the gingiva of ligatured and un-ligatured WT and Spock1-Tg mice in the presence or absence of CsA administration and/or experimental periodontitis." (PMID 38156070, 2023). "As previously reported, CsA-treated WT and Spock1-Tg mice showed distinct gingival overgrowth on the occlusal and buccal sides in response to ligature-induced periodontitis compared to ligature-treated WT and Spock1-Tg mice without CsA treatment." (PMID 38156070, 2023). "On the buccal side, periodontitis-induced gingival overgrowth in WT mice was comparable to that of Spock1-Tg mice without ligature." (PMID 38156070, 2023). "We then measured periodontitis-related gene expression in the gingiva of CsA-treated or untreated Spock1-Tg and WT mice, with or without ligatures." (PMID 38156070, 2023). "To investigate whether SPOCK-1 overexpression enhanced gingival overgrowth in the DIGO rodent model, we induced experimental periodontitis in both Spock1-Tg and WT mice by CsA treatment and assessed gingival overgrowth in these mice." (PMID 38156070, 2023). "Taken together, we considered that CsA-related EMT could be partially different from SPOCK1-related EMT in gingiva, but both contribute to gingival overgrowth under periodontitis." (PMID 38156070, 2023).
pituitary adenomas (1 paper, 2022). "While MMP14 and ADAM10 regulate cell migration and invasion in pituitary adenomas, no clear function for SPOCK1 has been described so far in pituitary tissue." (PMID 35370944, 2022).
prostate tumor (1 paper, 2019). "To investigate the efficacy of the targeting of SPOCK1 by API on the prostate tumor growth and metastasis cascade, we established a murine orthotopic xenograft model and monitored tumor metastasis via a non-invasive IVIS." (PMID 31182131, 2019).
Rett syndrome (1 paper, 2006). A severe neurodevelopmental disorder affecting the central nervous system.
schizophrenia (1 paper, 2024). A major psychotic disorder characterized by abnormalities in the perception or expression of reality. "We previously observed decreased SPOCK1 and SPOCK3 mRNA expression in the brain of subjects with schizophrenia, which shares genetic overlap with ASD." (PMID 38355786, 2024).
viral infection (1 paper, 2020). "The functions of SPARC/Osteonectin, Cwcv and Kazal-like Domains Proteoglycan 1 (SPOCK1), Zinc Finger and BTB Domain Containing 11 (ZBTB11), and myosin XVB (MYO15B) in viral infection are unclear." (PMID 32223537, 2020).
tumor (62 papers, 2015 to 2026). "Multiplex immunohistochemistry (mIHC) was performed to validate the spatial distribution of SPOCK1+ cancer-associated fibroblasts (CAFs) within the tumor microenvironment." (PMID 40837013, 2025). "CIBERSORT algorithm and Tumor Immune Estimation Resource (TIMER) were used to elucidate the association of SPOCK1 and POSTN expression with immune cell infiltration level." (PMID 36611136, 2023). "The SPOCK1 proteoglyan has been discovered as an oncogene with overexpression, promoting tumor formation and progression, and linked with poor survival rates." (PMID 37046698, 2023). "In our study, patients with high SPOCK1 expression showed significant enrichment of immune suppressive components in the tumor microenvironment, including tumor-associated macrophages, myeloid-derived suppressor cells (MDSCs), and regulatory T cells (Treg)." (PMID 38087364, 2023). "The SPOCK1 gene encodes a matricellular glycoprotein that belongs to a family of novel Ca2+‐binding proteoglycans and promotes cell migration in many tumours." (PMID 37753805, 2023). "To understand the potential association between SPOCK1 and tumor microenvironment (TME) remodeling, we evaluated the distribution differences of 29 TME signatures in the high and low SPOCK1 expression groups using the ssGSEA algorithm." (PMID 38087364, 2023). "In conclusion, these results suggest that SPOCK1 is highly associated with tumor malignant progression." (PMID 38087364, 2023). "Regarding chemotherapy, a number of studies have implicated SPOCK1 in the resistance of tumor cells to various drugs." (PMID 37046698, 2023). "SPOCK1 is associated with tumour size and TNM stage, promotes the epithelial‐mesenchymal transition (EMT) and activates PI3K/Akt signalling pathway to enhance the proliferative and invasive ability of CRC cells." (PMID 33660944, 2021). "The SPOCK1 gene is located on chromosome 5q31.2 and encodes a highly conserved glycoprotein testican-1 which was associated with tumor progression and prognosis as well as neurogenesis." (PMID 28155865, 2017). "Consistently, BLI and H&E staining revealed a lower tumor burden in SPOCK1-silenced groups, associated with a lower osteolytic area." (PMID 28103946, 2017). "SPOCK1 and its gene product testican-1 have been associated with tumor progression and prognosis of different cancer types." (PMID 28155865, 2017). "Moreover, upregulation of SPOCK1 was significantly associated with advanced clinical stages, larger tumor sizes, lymph node and distal metastases, and shorter OS, DSS, and DFS times of ccRCC patients." (PMID 36766694, 2023). "It has been demonstrated that overexpression of the SPOCK1 gene promoted the development and progression of tumors and is associated with shorter survival rates, indicating that it may become a viable anti-tumor therapeutic target." (PMID 37046698, 2023). "In summary, our study revealed for the first time that the SPOCK1 expression is associated with advanced stages, larger tumor sizes, and lymph node/distal metastases, and it was identified as an independent predictive marker for poor prognoses in patients with ccRCC." (PMID 36766694, 2023). "Furthermore, SPOCK1 is highly associated with immune checkpoint molecules in several cancers, suggesting that it may influence tumor–immune system interactions by modulating the tumor immune microenvironment, thereby promoting immune tolerance." (PMID 40837013, 2025). "CHD1L promotes tumor cell survival by upregulating SPOCK1 (see Control of Gene Expression and Signaling above), a matricellular glycoprotein that blocks apoptosis through activation of the PI3K/Akt signaling pathway." (PMID 40442742, 2025).
tumor (continued). "Spearman’s rho and statistical significance values were obtained for the correlation between SPOCK1 expression and tumor infiltration by different immune cells." (PMID 40001977, 2025). "Using SingleR, cell-type-specific scores were computed, revealing co-enrichment of CAF+SPOCK1 and malignant epithelial cells in spatially adjacent tumor regions." (PMID 40837013, 2025). "Spatial transcriptomics and multiplex immunohistochemistry (mIHC) further validated the spatial co-localization of SPOCK1+ CAFs and malignant epithelial cells in the tumor core, reinforcing the spatial-functional link between stromal and tumor cells." (PMID 40837013, 2025). "We observed that SPOCK1 is primarily expressed in CAFs, with significantly higher expression in tumor-derived CAFs compared to adjacent normal tissues." (PMID 40837013, 2025). "Sparc/Osteonectin, cwcv, and kazal-like domain proteoglycan 1 (SPOCK1) gene inhibits the apoptosis of tumor cells and is located in the nucleus and mitochondria of tumor cells." (PMID 40708997, 2025). "SPOCK1 expression was highest in CAFs, a cell type known to play a vital role in tumor development and metastasis." (PMID 40837013, 2025). "Single-cell analysis identified CAFs as the primary cell population expressing SPOCK1, with spatial mIHC confirming their close proximity to tumor cells." (PMID 40837013, 2025). "CHD1L-induced SPOCK1 expression also contributes to tumor progression, with elevated SPOCK1 levels correlating with increased metastasis, advanced tumor stage, and poor clinical outcomes for cancer patients." (PMID 40442742, 2025). "This is consistent with the higher mRNA expression levels of SPOCK1 in tumor patients compared to the normal group." (PMID 38087364, 2023). "SPOCK1 is considered a resident of the extracellular matrix, which inhibits the apoptosis of tumor cells and promotes EMT formation by participating in the activation of the TGF-β pathway." (PMID 38087364, 2023). "The promoter CpG islands of SPOCK1 were hypermethylated and promoted tumor progress in CRC similar to our research." (PMID 37779184, 2023). "SPOCK1 is considered to be one of the key regulatory genes involved in maintaining the dynamic balance of ECM in the tumor microenvironment." (PMID 38087364, 2023). "In the samples taken after neoadjuvant treatment, however, a significant decrease was observed in SPOCK1 expression in tumor cells, with a mean immune score of 1.3 (p < 0.001)." (PMID 37046698, 2023). "Consistent with our in vitro findings, IHC staining of SPOCK1 and vimentin in tumor tissues from Caki-1-SPOCK1- and Caki-1-shSPOCK1-injected mice showed the upregulation and downregulation of both proteins, respectively, compared to control mice." (PMID 36766694, 2023). "Taking into consideration the pro-tumor characteristics of SPOCK1, we utilized CMap to screen potential drugs based on the differential expression profile between high and low SPOCK1." (PMID 38087364, 2023). "In the last few years, one proteoglycan, namely, SPOCK1/testican-1 has been gaining more and more attention due to its tumor-promoting effects in cancer." (PMID 38139365, 2023). "Compared to other tumor types, little information is available on the effects of SPOCK1 on matrix-degrading proteases in ccRCC." (PMID 36766694, 2023). "Altogether, these results suggested that SPOCK1 promotes tumor progression by affecting these tumor and immune-related pathways, leading to a poor prognosis in CRC patients." (PMID 36611136, 2023). "By analyzing gene expression and tumor-infiltrating immune cells, the same study revealed that SPOCK1 level was correlated with several immune cells across cancers." (PMID 37046698, 2023). "We demonstrated significant correlations of high expression levels of SPOCK1 in tumor tissues with advanced clinical stages, larger tumor sizes, lymph node and distal metastases, and worse prognoses in patients with ccRCC." (PMID 36766694, 2023).